OC90 (otoconin 90)
Description:
Major protein of the otoconia, a calcium carbonate structure in the saccule and utricle of the ear. Together with OTOL1, acts as a scaffold for otoconia biomineralization: sequesters calcium and forms interconnecting fibrils between otoconia that are incorporated into the calcium crystal structure. Together with OTOL1, modulates calcite crystal morphology and growth kinetics. It is unlikely that this protein has phospholipase A2 activity.
Synonyms: PLA2L
Tractability: Antibody: UniProt places it where antibodies can reach, with medium confidence; UniProt predicts a signal peptide or a membrane-spanning region; its Gene Ontology location is reachable by antibodies, with medium confidence.
Gene: Protein-coding gene on chromosome 8 (132,024,216 to 132,059,382, reverse strand). Ensembl gene ENSG00000253117.
Subcellular location: Secreted
Gene Ontology:
Molecular function: calcium ion binding; phospholipid binding; phospholipase A2 activity; structural molecule activity
Biological process: otolith mineralization; phosphatidylcholine metabolic process; phosphatidylglycerol metabolic process; arachidonate secretion; lipid catabolic process; phospholipid metabolic process
Cellular component: extracellular matrix; extracellular region
Genetic constraint (gnomAD): Loss-of-function variants: 36 observed, 37.31 expected, observed/expected ratio (o/e) 0.96, 90% interval 0.74 to 1.27. The upper end of that interval is the gene's LOEUF score, 1.27, which puts it in group 5 of 6, group 1 being the genes least tolerant of losing a copy. Missense variants: 605 observed, 522.66 expected, observed/expected ratio (o/e) 1.16, 90% interval 1.08 to 1.24. Synonymous variants: 246 observed, 202.49 expected, observed/expected ratio (o/e) 1.21, 90% interval 1.09 to 1.35.
Homologues: Orthologues: chimpanzee OC90 (98% identical), macaque OC90 (95% identical), rabbit OC90 (75% identical), guinea pig OC90 (72% identical), pig OC90 (71% identical), rat Oc90 (69% identical), mouse Oc90 (69% identical), tropical clawed frog oc90 (41% identical), zebrafish oc90 (28% identical), Caenorhabditis elegans C03H5.4 (9% identical), Caenorhabditis elegans C07E3.9 (8% identical). Paralogues in human: PLA2G2F (11% identical), PLA2G1B (9% identical), PLA2G10 (9% identical), PLA2G2A (9% identical), PLA2G2D (9% identical), PLA2G2E (9% identical), PLA2G2C (8% identical), PLA2G5 (8% identical).
Diseases named in the same sentence as OC90 in open-access papers:
OC90 is named in the same sentence as 11 diseases in open-access papers, as found by Europe PMC text mining. Sharing a sentence is not in itself a finding about the gene and the disease. The quoted sentences say what the papers report.
invasive breast carcinoma (1 paper, 2019). A carcinoma that infiltrates the breast parenchyma. "Of note, 25% of invasive breast cancers, 20% of prostate cancers and 19% of lung adenocarcinomas show elevated OC90 gene expression." (PMID 30763339, 2019).
lung adenocarcinoma (1 paper, 2019). A carcinoma that arises from the lung and is characterized by the presence of malignant glandular epithelial cells. "Previously, OC90 amplification was observed in 20–40% of TNBCs, prostate cancer and lung adenocarcinoma in our recently published analyses." (PMID 30763339, 2019).
Skin cutaneous melanoma (1 paper, 2019). "Skin cutaneous melanoma (84%), uveal melanoma (58%) and testicular germ cell tumors (56%) have the highest proportion of OC90 expression in tumor tissues." (PMID 30763339, 2019).
Vertigo (1 paper, 2026). An abnormal sensation of spinning while the body is actually stationary. "Higher PSQI scores were also associated with increased levels of Otolin-1 and otoconin-90, both of which were independently related to vertigo severity." (PMID 41836934, 2026).
cancer (2 papers, 2010 to 2019). A tumor composed of atypical neoplastic, often pleomorphic cells that invade other tissues. "Likewise, expression of OC90 in tumors was observed in 19.93% of the thirty three cancer types in RNA-seq analysis of TCGA tumors by Toil." (PMID 30763339, 2019). "OC90 amplification is observed in 20–40% of TNBCs and in other cancers." (PMID 30763339, 2019).
tumor (1 paper, 2019). "In silico analysis of The Cancer Genome Atlas (TCGA) multi-tumor RNAseq cohorts revealed that OC90 is expressed in many tumor types at high prevalence and genomic amplification is associated with the elevated mRNA expression." (PMID 30763339, 2019). "Assuming normal function of OC90 is restricted to otolith development, OC90 has potential as a drug target, because knockdown in tumor tissues could be effective without having an impact on normal tissue function." (PMID 30763339, 2019).
OC90 also shares sentences with these, for which no sentence is quoted: Hypocalcemia (1 paper); prostate carcinoma (1); testicular germ cell tumor (1); triple-negative breast carcinoma (1); uveal melanoma (1).